ADGRG2 (adhesion G protein-coupled receptor G2)
Diseases named in the same sentence as ADGRG2 in open-access papers:
ADGRG2 is named in the same sentence as 66 diseases in open-access papers, as found by Europe PMC text mining. Sharing a sentence is not in itself a finding about the gene and the disease. The quoted sentences say what the papers report.
Ewing sarcoma (13 papers, 2013 to 2025). A small round cell tumor that lacks morphologic, immunohistochemical, and electron microscopic evidence of neuroectodermal differentiation. "In addition, ADGRG2 has been implicated as an immune-related gene with independent prognostic significance for Ewing sarcoma, and it has the potential for drug delivery in antibody-based sarcoma therapy." (PMID 38069309, 2023). "It has been shown that ADGRG2 was highly elevated in some solid tumors and can facilitate cell growth and invasion of various cancer cells, such as Ewing sarcoma, parathyroid tumor, hormone cell adenoma, etc.." (PMID 38069309, 2023). "In particular, ADGRG2 plays a significant role in Ewing sarcoma cell proliferation, parathyroid cell function, and male fertility." (PMID 38202747, 2023). "ADGRG2, an orphan aGPCR, plays a major role in male fertility, Ewing sarcoma cell proliferation, and parathyroid cell function." (PMID 34234254, 2021). "In addition, ADGRG2 accelerates the growth and spread of Ewing sarcoma cells in vitro and in vivo and as such, it is highly expressed in Ewing sarcomas compared to normal tissues and other sarcomas." (PMID 38202747, 2023). "Knocking down ADGRG2 in Ewing sarcoma cell lines led to a reduction in tumor growth and metastasis." (PMID 38202747, 2023). "A more recent surfaceome analyses revealed many new Ewing sarcoma cell surface targets including ENPP1 and CDH11 in addition to known IL1RAP, STEAP1, ADGRG2 and CD99, providing newer cell surface targets for immunotherapeutic application in Ewing sarcoma." (PMID 40442778, 2025). "ADGRG2/GPR64 was also over-expressed in MTC (log2FC = 1.42, p = 0.0049) as in a number of carcinomas derived from breast cancer, parathyroid tumors, Ewing sarcomas, prostate, kidney or lung, and the inhibition of its expression promotes invasiveness and metastatic spread." (PMID 35203352, 2022).
Azoospermia (7 papers, 2018 to 2026). Absence of any measurable level of sperm,whereby spermatozoa cannot be observed even after centrifugation of the semen pellet. "Although TEX11 and ADGRG2 defects are frequently described in men with azoospermia, most of the causal gene defects found to date are private (i.e. identified in a small number of consanguineous families)." (PMID 31024732, 2019). "In addition, analysis of the CFTR gene is routinely performed in men with obstructive azoospermia and mutations in the ADGRG2 gene have been recently described to cause a similar phenotype." (PMID 29527098, 2018). "Previous studies of ADGRG2-positive patients with obstructive azoospermia have been limited to histology of the epididymis, and here we show the first examples of hypospermatogenesis identified from testicular biopsy in two patients with an ADGRG2 nonsense mutation." (PMID 30389958, 2018). "Congenital absence of the vas deferens (CAVD) is a major cause of obstructive azoospermia and male infertility, with its genetic etiology primarily associated with CFTR (autosomal recessive) and ADGRG2 (X-linked) mutations." (PMID 42199298, 2026). "ADGRG2 encodes a G-protein coupled receptor and is responsible for an X-linked form of vasal agenesis, typically presenting as isolated obstructive azoospermia without systemic CF symptoms." (PMID 41009940, 2025). "Obstructive azoospermia commonly is caused by CBAVD(Congenital Bilateral Aplasia of the Vas Deferens), mainly due to the cystic fibrosis transmembrane conductance regulator (CFTR) and adhesion G protein-coupled receptor G2(ADGRG2) mutations." (PMID 39402445, 2024). "Isolated congenital bilateral absence of vas deferens (iCBAVD) in men results in obstructive azoospermia and is mainly caused by pathogenic variants in cystic fibrosis transmembrane conductance regulator (CFTR) or adhesion G protein‐coupled receptor G2 (ADGRG2)." (PMID 37489040, 2023). "ADGRG2-related infertility presents with bilateral absence of the vas, obstructive azoospermia, and intact pulmonary and pancreatic function." (PMID 41009940, 2025). "Current examples are TEX15 and NPAS2 in non-obstructive azoospermia and ADGRG2 in obstructive azoospermia." (PMID 29527098, 2018).
male infertility (7 papers, 2008 to 2026). The inability of the male to effect fertilization of an ovum after a specified period of unprotected intercourse. "The largest AFD among all SNPs was 0.60 in the ADGRG2 gene, which was associated with fluid dysregulation and male infertility and decidualization of endometrial stromal cells." (PMID 30744549, 2019). "A recent methodological evolution which tends to be generalized is not to use in the first approach CFTR mutation-targeted tests but to directly offer a comprehensive scanning by NGS methodology of a panel of genes including CFTR, ADGRG2 and other genes linked to male infertility." (PMID 32025909, 2021). "Therefore, a specific agonist of AGTR2 should be considered for the development of therapeutic methods to treat male infertility caused by impaired ADGRG2-Gq-CFTR signaling, such as that observed in CF patients." (PMID 29393851, 2018). "If the CAVD man has no mutation after comprehensive CFTR testing and normal renal imaging, an ADGRG2 analysis should be suggested, especially if there is a family history of male infertility." (PMID 32025909, 2021). "Therefore, ADGRG2 has emerged as an important target for drug development for bone cancers and male infertility." (PMID 38202747, 2023). "Knockout of an orphan G-protein-coupled receptor (GPCR), ADGRG2 (adhesion G-protein-coupled receptor G2), results in male infertility due to dysregulated fluid reabsorption in the efferent ductules, suggesting an active role for this cell surface receptor in regulating these processes." (PMID 29393851, 2018). "Therefore, manipulation of the signaling components of the ADGRG2-Gq/β-arrestin-1/CFTR complex by small molecules may be an effective therapeutic strategy for male infertility." (PMID 29393851, 2018). "We have also identified putatively causal variants in seven genes validated as aetiological factors of male infertility, such as SPAG17, REC114, TERB1, DNAH6, ADGRG2, MAMLD1, and USP26." (PMID 39678461, 2024).
Infertility (5 papers, 2018 to 2021). "Thanks to high-throughput approaches such as whole exome sequencing (WES) and comparative genomic hybridization (CGH) arrays, novel X-linked gene mutations (e.g., TEX11 and ADGRG2) have been discovered as causative factors of different infertile phenotypes." (PMID 31875237, 2021). "Adgrg2-knockout male mice show sperm loss due to obstructive fluid stasis, while ADGRG2 mutations cause OA in the infertile male patients." (PMID 30389958, 2018). "Previous studies have found that knockout of the orphan receptor ADGRG2 causes infertility and fluid reabsorption dysfunction in the efferent ductules, indicating important roles for GPCR signaling in male reproductive functions." (PMID 29393851, 2018). "Following segregation analysis of the mutation in all available family members confirmed co-segregation of the ADGRG2 variant with OA in all infertile males." (PMID 30389958, 2018). "Notably, three loss-of-function mutations in the ADGRG2 gene were reported in infertile males with OA." (PMID 30389958, 2018). "We next examined how the molecular determinants of ADGRG2/G protein subtype interactions contribute to the function of ADGRG2 infertility in vivo." (PMID 29393851, 2018). "Interestingly, Adgrg2-mutant mice develop fluid accumulation in the deferent ducts, leading to an obstructive infertility phenotype, which resembles that observed in men with ADGRG2 mutation." (PMID 33806855, 2021). "On the other hand, targeted studies on highly specific infertile phenotypes have successfully identified a novel gene for congenital absence of vas deferens (ADGRG2) and for complete asthenozoospermia due to primary ciliary dyskinesia (PIH1D3)." (PMID 31875237, 2021).
sarcoma (4 papers, 2019 to 2023). A usually aggressive malignant neoplasm of the soft tissue or bone. "Antibodies targeting ADGRG2 accumulate in bone and soft tissue sarcomas, but they do not accumulate in the epididymis in vivo." (PMID 38202747, 2023).
adenoma (1 paper, 2022). A neoplasm arising from the epithelium. "SSTR1 was highly upregulated in invasive adenoma (log2FC = 9.14, p = 0.005) as well as the adhesion receptor ADGRG2 (log2FC = 5.26, p = 0.026), the serotonin receptor HTR4 5 (log2FC = 3.68, p = 0.007) and the prostaglandin receptor PTGER2 (log2FC = 3.06, p = 0.038)." (PMID 35203352, 2022).
atherosclerosis (1 paper, 2023). A disease characterized by the build-up of fatty material and calcium deposition in the arterial wall resulting in partial or complete occlusion of the arterial lumen. "In line with this, upregulation in ADGRG2 transcripts has been reported during the transformation of quiescent human coronary artery smooth muscle cells to a proliferative and migratory phenotype observed in atherosclerosis." (PMID 38132326, 2023).
chronic hepatitis (1 paper, 2023). An active inflammatory process affecting the liver for more than six months. "The ADGRG2 expression was more elevated in liver cirrhosis and hepatocellular carcinoma than in the normal and chronic hepatitis groups, which may imply that ADGRG2 was tied to inflammation and the occurrence of HCC." (PMID 38069309, 2023).
cystic fibrosis (1 paper, 2018). Autosomal recessive disorder caused by pathogenic variants in the CFTR gene (cystic fibrosis transmembrane conductance regulator), which encodes a chloride and bicarbonate channel expressed in epithelial cells, and follow the diagnosis criteria. "Notably, we found that ADGRG2 and Gq regulate fluid reabsorption in the efferent ductules via the activation of CFTR, an important ion channel whose mutation leads to cystic fibrosis." (PMID 29393851, 2018).
diabetic nephropathy (1 paper, 2018). "In addition, Nephroseq data suggest that ADGRG2 is upregulated in diabetic nephropathy (human, mouse model), CKD (human) as well as in the mouse Berthier model of lupus nephritis with proteinuria." (PMID 29468160, 2018). "Increased expression levels were found for ADGRL2, ADGRL4, ADGRE1, ADGRE5, ADGRG2, and ADGRG6 in lupus nephritis and diabetic nephropathy, whereby ADGRL2, ADGRL4 and ADGRE5 were also upregulated in IgA nephropathy." (PMID 29468160, 2018).
hepatocellular carcinoma (1 paper, 2023). A malignant tumor that arises from hepatocytes. "In addition, research has found that miR-326 inhibited the proliferation and migration of hepatocellular carcinoma cells by targeting ADGRG2, and the combination of ADGRG2 and miR-326 exhibited better diagnostic potential." (PMID 38069309, 2023). "Additionally, the expression of ADGRG2 is substantially positively related to inflammatory cytokines, and data showed a marked increase in ADGRG2 in patients with liver cirrhosis and hepatocellular carcinoma from GSE89377." (PMID 38069309, 2023). "Adhesion G protein-coupled receptor G2 (ADGRG2) is an orphan adhesion G protein-coupled receptor (GPCR), which performs a tumor-promoting role in certain cancers; however, it has not been systematically investigated in hepatocellular carcinoma (HCC)." (PMID 38069309, 2023).
hypospadias (1 paper, 2022). Hypospadias is the displacement of the urethral meatus on the ventrum of the penis. "It is remarkable that neither CFTR nor ADGRG2 variants were identified in hypospadias/CAVD patients." (PMID 36437957, 2022).
liver cancer (1 paper, 2023). An epithelial or non-epithelial malignant neoplasm that arises from the liver. "ADGRG2 not only enhanced the proliferation and migration of liver cancer cells but was also closely related to tumor immune infiltration and immune checkpoints." (PMID 38069309, 2023). "In conclusion, ADGRG2 may serve as a novel biomarker and drug target for HCC diagnosis, immunotherapy, and prognosis and was related to neutrophils and the inflammatory process of liver cancer development." (PMID 38069309, 2023). "The expression of ADGRG2 was negatively correlated with the PPAR signaling pathway, and one of the members of PPARγ mainly mediated the antiangiogenic process and may be a therapeutic target for liver cancer." (PMID 38069309, 2023).
liver diseases (1 paper, 2023). "We wondered whether ADGRG2 participated in inflammation as part of liver diseases." (PMID 38069309, 2023).
Nephroblastoma (1 paper, 2023). An embryonal neoplasm characterized by the presence of epithelial, mesenchymal, and blastema components. "We screened four highly expressed m6A-related genes (ADGRG2, CPD, CTHRC1, LRTM2) in nephroblastoma and constructed an effective diagnostic model based on these genes." (PMID 37938417, 2023).
parathyroid adenomas (1 paper, 2021). "We have previously shown that ADGRG2 is enriched in parathyroid glands, is upregulated in parathyroid adenomas from patients with primary hyperparathyroidism, and its activation by P-15 elevates PTH secretion." (PMID 34234254, 2021).
renal carcinoma (1 paper, 2018). A carcinoma arising from the epithelium of the renal parenchyma or the renal pelvis. "As detailed below, our literature search identified publications describing five aGPCRs correlated with kidney disease including renal cancer: Adgrb1, Adgrg2 (Gpr64), Adgrl4, Adgrg3, and Adgrf5." (PMID 29468160, 2018).
virus infection (1 paper, 2018). "Both ADGRG2 WT and G protein subtype mutants were conditionally expressed in the efferent ductules via virus infection under the 1 kb ADGRG2 promoter." (PMID 29393851, 2018). "To investigate whether the sperm production phenotype was related to fluid reabsorption, we isolated the efferent ductules after virus infection with the WT ADGRG2 or one of the mutants and measured the luminal area after ligation." (PMID 29393851, 2018).
cancer (11 papers, 2013 to 2025). A tumor composed of atypical neoplastic, often pleomorphic cells that invade other tissues. "Meanwhile, ADGRG2 was associated with cancer-related signaling pathways such as JAK-STAT, MAPK, calcium, and the PPAR signaling pathway." (PMID 38069309, 2023). "Similarly, tubulin alpha chain 1C (TUBA1C), adhesion G‐protein coupled receptor G2 (ADGRG2), and nectin‐4 have been associated with cell migration and proliferation, albeit in cancer cell types." (PMID 39895030, 2025). "Targeting ADGRG2 with antagonists holds considerable therapeutic potential for treating diseases linked to its abnormal signaling, particularly in reproductive health and cancer." (PMID 39796025, 2024). "This could have significant therapeutic benefits for diseases linked to ADGRG2 dysfunction, such as reproductive disorders and cancers." (PMID 39796025, 2024). "Treatment of HCC cells with modulated electro-hyperthermia (mEHT)-induced apoptosis led to a decreased mRNA expression of ADGRG2, suggesting that ADGRG2 may act as a cancer-causing gene in HCC." (PMID 38069309, 2023). "ADGRG2 is highly expressed in several human cancer cell lines including 8 human RCC cell lines: CAKI-1, 786-0, A498, ACHN, SN12-C, (all ccRCC), TK-10, RXF 393, and UO-31." (PMID 29468160, 2018). "Functional enrichment analysis suggested that ADGRG2 may be involved in cancer pathways and immune-related pathways." (PMID 38069309, 2023). "However, the systematic analysis of the expression, prognosis, and treatment of ADGRG2 in cancers still remains unexplored." (PMID 38069309, 2023). "In this study, we used a combination of bioinformatics and experimental validation methods to systematically evaluate the expression of ADGRG2 in HCC, as well as its correlation with diagnosis, prognosis, cancer occurrence and development, immune infiltration, and inflammation." (PMID 38069309, 2023). "Richter and coworkers demonstrated that inhibition of Adgrg2 expression impaired colony formation in vitro (A673, SB-KMS-KS1 and TC-71) and suppressed local tumor growth and metastasis in an immunodeficient mouse xenograft model of human cancer [SB-KMS-KS1/Rag2(−/−)γC(−/−)]." (PMID 29468160, 2018).
tumor (11 papers, 2018 to 2025). "Then, the up-regulated expression of ADGRG2 was verified in unpaired HCC samples (202 normal tissues vs. 243 tumor tissues) in ICGC_LIHC, paired HCC tissues (50 pairs) in TCGA, and the GEO database." (PMID 38069309, 2023). "The correlation between CTHRC1 and tumor is the most studied, followed by ADGRG2, while the correlation between CPD and LRTM2 and tumor is less studied." (PMID 37938417, 2023). "To summarize, ADGRG2 may be closely related to neutrophils and NETs and influence the tumor microenvironment to promote the formation and progression of HCC." (PMID 38069309, 2023). "Notably, ADGRG2 was dramatically correlated with neutrophils according to five algorithms in HCC, and most markers in neutrophils were connected with tumor-associated neutrophils (TAN) and inflammation." (PMID 38069309, 2023). "ADGRG2 may affect tumor immunity and the inflammatory microenvironment through collecting neutrophils and further releasing NETs." (PMID 38069309, 2023). "Conversely, ADGRG2 was underexpressed in endometrial carcinoma and may be tumor-suppressing." (PMID 38069309, 2023).
infection (2 papers, 2017 to 2018). The state of being infected such as from the introduction of a foreign agent such as serum, vaccine, antigenic substance or organism. "Specifically, conditional infection of the Gs/Gq double signaling-deficient mutant ADGRG2-HM696AA or the Gq signaling-deficient mutants Y708A and RK803EE did not result in differing levels of accumulation in the efferent ductules compared with those in Adgrg2-/Y mice infected with a control virus." (PMID 29393851, 2018).
ADGRG2 also shares sentences with these, for which no sentence is quoted: breast carcinoma (5 papers); endometrial cancer (2); myxofibrosarcoma (2); asthenozoospermia (1); bone tumors (1); cholangiocarcinoma (1); chondrosarcoma (1); chordoma (1); congenital heart defects (1); coronary artery disease (1); dedifferentiated liposarcoma (1); endometrial adenocarcinoma (1); endometrial endometrioid adenocarcinoma (1); endometrial tumors (1); endometrioid endometrial carcinoma (1); endometriosis (1); fibrosarcoma (1); Insulin resistance (1); kidney disease (1); leiomyosarcoma (1); liposarcoma (1); liver cirrhosis (1); lung carcinoma (1); lupus nephritis (1); malignant peripheral nerve sheath tumor (1); mantle cell lymphoma (1); medulloblastoma (1); melanoma (1); mesenchymal neoplasms (1); myxoid liposarcoma (1).
A further 15 diseases each share a sentence with ADGRG2 in 1 paper.